IL6 (interleukin 6)
Diseases named in the same sentence as IL6 in open-access papers (continued):
Sharing a sentence is not in itself a finding about the gene and the disease.
Cachexia (continued). "The inflammatory cytokines produced by tumor cells and leukocytes, including tumor necrosis factor alpha (TNF-α) and interleukin-1, interleukin-6, and interleukin-8 (IL-1, IL-6, and IL-8), are demonstrated to be the major drivers of cachexia." (PMID 34760698, 2021). "Accordingly, the changes in energy metabolism induced by the chronic action of proinflammatory cytokines, mainly by IL-6, in cancer cachexia alter insulinemia and glucose utilization for energy." (PMID 33809200, 2021). "Although our avatar data suggest a central role for IL-6 from malignant cells in cachexia, as also observed in C26 cachexia models, our results linking this to patient phenotypes is modest." (PMID 33851955, 2021). "We further define mechanisms by which tumor cells elicit cachexia by inducing crosstalk between fat and muscle, mediated via a feed-forward, IL-6 trans-signaling loop." (PMID 33851955, 2021). "In summary, the role of TAMs in CRC-associated cachexia depends on the M1/M2 macrophage ratio in TME, as well as the immune response mediators produced by these cells (mainly IL-1 and IL-6)." (PMID 33557173, 2021). "In cancer patients, the inflammatory cytokines produced by tumor cells and leukocytes like tumor TNF-α and IL-1, IL-6, and IL-8 are major drivers of cachexia, which affects several tissues, including skeletal muscle, brain, liver, and so on." (PMID 34760698, 2021). "Parameters of cachexia phenotype were completely normalized in Il1β−/−/CKD mice but were only partially rescued in Il6−/−/CKD and Tnfα−/−/CKD mice." (PMID 34302016, 2021). "The use of various cancer-induced cachexia in vitro models allowed the demonstration of a key involvement of IL-6/STAT3 signaling in the process of skeletal-muscle wasting." (PMID 33557173, 2021). "Among the pro-inflammatory mediators, the ones mainly implicated in the pathogenesis of cachexia are TNF-α, IL-6, IL-1, IL-8, and IFN-γ." (PMID 34832866, 2021). "As IL-6 induces glucocorticoid secretion and muscle wasting in cancer cachexia animal model reportedly depends on intact glucocorticoid signaling in skeletal muscle, we studied the role of glucocorticoid on bone marrow MSCs differentiation." (PMID 33801569, 2021). "TNFα, IL-6, IL-8, IL-1β, and IFNγ are considered to be the major inflammatory mediators of cancer-induced cachexia, which have been demonstrated to be elevated in various animal models of cancer." (PMID 32722688, 2020). "It have been identified that four pro-inflammatory cytokines including tumor necrosis factor alpha (TNF-α, initially named cachectin), interferon-γ (IFN-γ), interleukin-6 (IL-6) and interleukin-1 (IL-1) contributed to the cachexia syndrome." (PMID 32139788, 2020). "A more recent study demonstrated how IL-1 beta (IL-1β) increased SM catabolism in a rodent model of CC by promoting a cachexia-associated gene expression pattern in the hypothalamic–pituitary–adrenal (HPA) axis, differently from IL-6 and IL-1α." (PMID 32195193, 2020). "Other pathways which were previously reported in cachexia such as IL-6 signaling, STAT3 signaling, protein ubiquitination pathway and mitochondrial dysfunction were also identified." (PMID 33334063, 2020). "Activin A and IL‐6 are both suggested to contribute to cachexia, and accordingly, their individual role in development of this condition has been a central topic of research." (PMID 31436048, 2020). "We found that GE5, GE50 and Rb1 can reduce the inflammatory cytokines TNF-α and IL-6 in cancer cachexia mice." (PMID 32020864, 2020). "Inflammatory cytokines, especially IL-6, are an important driver of muscle wasting in chronic disease that leads to cachexia." (PMID 31947724, 2020). "Several of these upstream regulators such as IL-1 alpha, IL4, IL6, LIF, TNF have known causal roles in cachexia validated using experimental models." (PMID 33334063, 2020).
Cachexia (continued). "Although IL-6 is not considered the sole inducer of cachexia, an increased level of IL-6 is a typical symptom found in cancer patients and is one of the major factors in the development of cancer cachexia." (PMID 33086629, 2020). "In PC-dependent cachexia, interleukin 1 (IL-1), interleukin 6 (IL-6) Interleukin 8 (IL-8), and tumor necrosis factor α (TNF-α) are the most common pro-inflammatory cytokines." (PMID 32466362, 2020). "Activin A and interleukin 6 (IL‐6) are among the best studied factors that seem to be important, and several studies support their individual role in cachexia development." (PMID 31436048, 2020). "Treadmill training has been also been shown to similarly augment mTOR signaling and augment mitochondrial quality control in the presence of systemic IL-6 overexpression, a major contributor to the activation of cachexia in cancer patients." (PMID 33584337, 2020). "In observational studies, magnesium intake was found to be inversely related to cachexia-associated inflammatory cytokines such as CRP, TNFα, and IL-6, in a dose-dependent manner." (PMID 31947724, 2020). "In order to better understand the regulation of the muscular APR production during cancer cachexia and its association with muscular atrophy, we investigated the role of IL-6 as a mediator of their muscular induction during cancer cachexia." (PMID 33142864, 2020). "On the contrary, IL-6 inhibition has a more beneficial effect by increasing lean mass and skeletal muscle, counteracting cachexia." (PMID 32183053, 2020). "This pattern of weight gain during treatment with an IL-6 pathway inhibitor is in line with research implicating elevated concentrations of IL-6 in the development of cachexia as seen in clinical populations." (PMID 32878032, 2020). "Some authors consider that the significance of IL-6 overexpression in skeletal muscle in cachexia is the same as in the muscle with inflammatory pathology, increasing the disease progression." (PMID 32775472, 2020). "IL-6 is considered to be a master regulator of the acute phase response in patients with cachexia and can raise tumor growth in the cancer cachexia progress." (PMID 32020864, 2020). "First and foremost, circulating interleukin-6 (IL-6) is recognized as one of the main factors leading to the outbreak of cachexia." (PMID 32195193, 2020). "We previously found that the human TOV21G cells secrete IL‐6 that induces autophagy in reporter cells and cachexia in mice." (PMID 31436048, 2020). "A higher IL-6 gene expression level was confirmed in patients with cachexia developing during the studied neoplasms compared to the group without cachexia and healthy people." (PMID 33327591, 2020). "Mice s.c. injected with LLC or B16 melanoma cells showed cachexia development, with reduced body weights, WAT loss, muscle wasting, and increased serum TNF-α and IL-6 levels." (PMID 33329046, 2020). "It is well-established that C26 cachexia alters the plasma levels of several soluble factors including TNFα, IL-1β and IL-6 which can accelerate the activity of key proteolytic pathways involved in the development of muscle weakness." (PMID 33014286, 2020). "Higher levels of IL-6, IL-8, IL-1β and TNFα have been demonstrated in patients with confirmed cachexia." (PMID 33327591, 2020). "Next, in line with the changes in circulating IGF1 and IL6, we sought to investigate the cachexia-related molecular changes within the skeletal muscle of HCT116 and mHCT116 hosts." (PMID 31915140, 2020). "Evidences have suggested that elevated IL-6 levels in most experimental models of cachexia are responsible at least in part for cachexia-induced muscle atrophy." (PMID 31293430, 2019). "Conversely, serum IL-6 level was significantly elevated in both male and female cancer cachexia patients, which strongly implied that IL-6 plays an important role in the progress of cancer cachexia." (PMID 31788012, 2019).
Cachexia (continued). "Raised serum C-reactive protein (CRP), a biomarker for systemic inflammation, interleukin 6 (IL6), and growth differentiation factor-15 (GDF-15) are thought to be associated with cachexia." (PMID 31323984, 2019). "Inflammation is the driving force of cachexia, and the most commonly implicated proinflammatory cytokines in cachexia include tumor necrosis factor α (TNF-α), interleukin (IL) 1, IL-6, and IL-8." (PMID 31069007, 2019). "Lastly, we analyzed the correlation between lipid metabolism parameters and IL-6 in cancer cachexia patients of different genders." (PMID 31788012, 2019). "Circulating IL-6 is a driver of muscle wasting in the ApcMin/+ mouse model of cancer cachexia, and cachexia is accompanied by altered mitochondrial dynamics and increased FIS-1 protein expression." (PMID 30918582, 2019). "There exists considerable evidence suggesting TNF-a and IL-6 are the most relevant cytokines inducing muscle wasting and promoting the development of cachexia." (PMID 31615487, 2019). "Serum concentrations of IL-6 also increased in parallel with worsening cachexia and gut barrier permeability." (PMID 31842339, 2019). "Lastly, the correlations between plasma interleukin-6 (IL-6) and lipid metabolism parameters in cachexia patients of different genders were analyzed." (PMID 31788012, 2019). "In some cases, the symptoms of cachexia have been alleviated by inhibiting tumor growth, stimulating appetite, and removing tumor-derived pro-cachectic factors such as IL-6 and myostatin." (PMID 29662645, 2018). "Findings from the Apc (Min/+) cachexia mouse model suggest that systemic IL-6 is necessary for adipose and skeletal muscle atrophy." (PMID 30081609, 2018). "The IL6/STAT3 pathway is thought to induce muscle wasting in cachexia experimental models via two routes." (PMID 30072615, 2018). "It has been established in various mouse models of cachexia that IL-6 catabolic signaling in cachexia is exerted through the transcription factor STAT3." (PMID 30081609, 2018). "LIF is a tumor-derived factor that is involved in the development of cachexia/anorexia, alongside IL-6 and TNFα." (PMID 30513935, 2018). "Using these approaches, we identified one cytokine, interleukin-6 (IL-6), as a driver, not only of cachexia, but also of gut barrier alterations and microbial dysbiosis in a preclinical model of cancer cachexia." (PMID 29719601, 2018). "Toxoplasma cachexia is characterized by a loss of 20% in body mass, including fat and muscle, transient anorexia and an acute elevation in the hallmark cachexia cytokines IL-1, TNF and IL-6." (PMID 30379866, 2018). "Correlation analyses showed significantly positive association between serum IL-6 and FFA in both early- and late-stage cachexia." (PMID 29338749, 2018). "Our results therefore indicate that targeting eIF4A reduces the abundance of multiple proteins, including iNOS, STAT3 and IL-6, which are essential in the onset of cachexia." (PMID 29849089, 2018). "Earlier studies have reported that serum IL-6 is elevated chronically in cachexia and Duchenne muscular dystrophy (DMD) patients and acutely after exercise, and decreases rapidly within an hour to pre-exercise levels." (PMID 29872072, 2018). "IL-6 has been proposed as a key driver of cachexia in the C26 model, but this remains controversial." (PMID 29719601, 2018). "Conditioned medium from the cachexia-inducing cancer cells contained high levels of IL-6 and neutralizing this cytokine strongly reduced the autophagy-inducing activity." (PMID 28515477, 2017). "This review will discuss the implications for IL-6-induced STAT3 signaling in the regulation of cachexia-induced mitochondrial dysfunction." (PMID 28785374, 2017). "Altered expression of proteins involved in mitochondrial biogenesis and fusion were also detected as signs of initiation of cachexia in skeletal muscles through interleukin (IL)-6 regulation in ApcMin/+ mice." (PMID 29255650, 2017).
Cachexia (continued). "Their studies were performed, therefore, in 14 week old mice weighing an average of 12 grams, rendering this a mouse model of cachexia, which had the potential to complicate the role of IL-6 in the development of MCD diet-induced NASH development." (PMID 28632778, 2017). "The concentration of IL-6 was seen to gradually rise during the early stages of cachexia followed by a sharp rise in the week prior to death." (PMID 28384249, 2017). "Given the low abundance of IL-6R on muscle cells, it is possible that, during cachexia, autophagy induced by IL-6 trans-signaling plays a dominant role." (PMID 28515477, 2017). "Systemic IL-6 overexpression in ApcMin/+ mice had elevated FIS-1 protein levels prior to the onset of cachexia." (PMID 28785374, 2017). "The primary catabolic mediators of cachexia include proinflammatory cytokines such as tumor necrosis factor alpha (TNFα), interferon gamma (IFNγ), and interleukin‐6 (IL‐6)." (PMID 28264935, 2017). "We found that serum TNFα and IL-6 levels were elevated in wild-type LLC tumor-bearing mice that developed cachexia, while IL-1β level remained unchanged." (PMID 28536426, 2017). "Others and we have shown that IL-6 alone is sufficient to induce cachexia both in vitro and in vivo." (PMID 28149280, 2016). "The Kampo formula Hochuekkito (TJ-41) and the natural herb Coptidis rhizoma improved cachexia symptoms in mice induced by Colone-26 adenocarcinoma via a reduction in IL-6 levels." (PMID 27064118, 2016). "We have demonstrated in two mouse models of cancer-induced cachexia that in pre-cachectic mice, even before the onset of the weight-losing phase of the syndrome, tumor-induced IL-6 has altered the capacity of the liver to respond to caloric deprivation." (PMID 27829137, 2016). "Elevated serum IL-6 levels have been observed in C26 and ApcMin/+ mouse models of cancer cachexia, and systematic administration of IL-6 to these mice resulted in depletion of skeletal muscle and adipose tissue and ultimately led to death." (PMID 26856534, 2016). "It has been reported that, in cachexia, tumor-derived inflammatory cytokines such as IL-6, TNF-α, and IL-1 are critical inducers of muscle wasting and fat depletion." (PMID 27064118, 2016). "The ApcMin/+ mouse exhibits an IL-6-dependent cachexia, which has a slow onset and progression over a longer time period when compared to other preclinical cachexia models." (PMID 27449092, 2016). "These cachectic mediators include TNFα, Myostatin, Activin, other members of the TGF-β superfamily, and the well-known driver of cachexia, Interleukin-6 (IL-6)." (PMID 28149280, 2016). "Accordingly, the blockade of IL-6 with a specific antibody attenuated cachexia severity and muscle wasting in C26 mice." (PMID 27642498, 2016). "We have found systemic IL-6 adversely affects skeletal muscle protein turnover and liver metabolism during the progression of cachexia." (PMID 27449092, 2016). "We have previously found the induction of MuRF-1 and Atrogin-1 gene expression during cachexia progression, and systemic IL-6 inhibition can suppress muscle protein degradation in ApcMin/+ mice." (PMID 27449092, 2016). "Earlier studies have shown that ApcMIN mice exhibit uncontrollable systemic elevations in inflammatory factors IL-6, IL-1b, and TNF-a, with these same factors also associated with cachexia in patients." (PMID 26933816, 2016). "While several cytokines have been implicated to mediate muscle wasting during cancer cachexia, IL-6 has been shown to play a critical role in cachexia progression in both human patients and in several preclinical cancer models." (PMID 27449092, 2016). "IL-6 is capable of induce cachexia altering the metabolism of lipids and proteins as well as impairing myogenic differentiation in certain types of cancer." (PMID 27330885, 2016).
Cachexia (continued). "Hepatic STAT-3 phosphorylation, however, is also considered to be an inflammatory marker and is sufficient to induce an IL-6 dependent muscle atrophy in the ApcMin/+ mouse with cachexia progression." (PMID 25789991, 2015). "IL-6 has been reported to be involved in early stages of cachexia and a study conducted in patients with mixed tumor types showed IL-6 levels gradually increased during early stages of cachexia followed by rapid increase prior to death." (PMID 26508820, 2015). "C-reactive protein, albumin, hemoglobin, and IL-6, biochemical markers of cachexia, were also evaluated." (PMID 26732354, 2015). "Previous reports demonstrated that STAT3 activation induced by IL-6 is per se sufficient to induce muscle fiber wasting in vitro as well as in vivo and that STAT3 inhibition would abolish skeletal muscle wasting downstream of IL-6 in cancer cachexia models." (PMID 25460504, 2015). "The interaction between cachexia and tumours increased the amount of IL-6 in subcutaneous adipose tissue and increased the IL6/IL-10 ratio, but not in visceral adipose tissue." (PMID 26508818, 2015). "In this study healthy mice injected with docetaxel showed acute skeletal muscle wasting and elevation of IL-6 in serum and muscle, suggesting that IL-6 is the key factor in the induction of cachexia." (PMID 25797259, 2015). "Both cachectic cancer patients and animal models of cachexia have elevated proinflammatory cytokine (e.g. TNFα, IL-1, IL-6) expression in the bloodstream, suggesting that these factors play a role in the development of cachexia." (PMID 26709824, 2015). "The murine C-26 cachexia model has shown that increasing levels of IL-6 correlated with the development of cachexia; treatment with an IL-6 neutralizing antibody attenuated the development of weight loss." (PMID 24624094, 2014). "The association of SELP-rs6136, IL6-rs1800796 and AKT1-rs1130233 polymorphisms with cachexia as well as the correlation between cachexia and the candidate polymorphisms and overall survival were analyzed." (PMID 25238546, 2014). "Increasing the levels of IL-6 has been shown to correlate with development of cachexia in certain mouse models." (PMID 24877061, 2014). "Cytokines such as IL-6 appear to be key drivers of the wasting process in this cancer cachexia model." (PMID 24667661, 2014). "Both cachexia and pre-cachexia are frequently associated with inflammation; an imbalance between pro-inflammatory (TNF-α, Interleukin (IL)-6, and IL-1) and anti-inflammatory (e.g., IL-4, IL-12, IL-15) cytokines is considered to contribute to the pathogenesis." (PMID 25988122, 2014). "Our study demonstrates that the SJDBT ameliorates cancer-induced anorexia and cachexia in CT-26 tumor-bearing mouse model by altering the production of IL-6, MCP-1, PYY, and GLP-1." (PMID 24963216, 2014). "On the other hand, myostatin inhibition, IL-6 antagonism and synthetic ghrelin administration are examples of promising treatments in cachexia animal models." (PMID 24782779, 2014). "Treatments designed to bind to IL-6 and inhibit its effect have demonstrated improvement in cachexia." (PMID 24877061, 2014). "Which factors downstream of IL-6 mediate effects on cachexia are still being elucidated but likely involve the transcription factor STAT3, which we describe in more detail below." (PMID 24877061, 2014). "Circulating levels of IL-6 are highest during the later stages of cachexia in the ApcMin/+ mouse similar to when we observe the onset of hypogonadism." (PMID 24285707, 2013). "We next treated ApcMin/+ mice exhibiting initial body weight loss with an IL-6 receptor antibody for two weeks to block systemic IL-6 signaling including both classical and trans IL-6 signaling, during a pivotal time point in the progression of cachexia." (PMID 24285707, 2013). "Elevated levels of IL-6 are found in weight-losing cancer patients, and antibodies against IL-6 will suppress the development of cachexia in animals to some extent." (PMID 24381940, 2013).